PML (PML nuclear body scaffold)
Diseases named in the same sentence as PML in open-access papers (continued):
Sharing a sentence is not in itself a finding about the gene and the disease.
rheumatoid arthritis (4 papers, 2012 to 2025). A chronic, systemic autoimmune disorder characterized by inflammation in the synovial membranes and articular surfaces. "In fact, our microarray analyses demonstrate that knockdown of PML is associated with a network of genes involved in chronic inflammation-related diseases, such as Rheumatoid arthritis and Atherosclerosis." (PMID 22947142, 2012). "Ectopic expression of SUMO1 increases SUMOylation of nuclear PML proteins, PML NBs and protects rheumatoid arthritis synovial fibroblasts against Fas-induced apoptosis." (PMID 23316480, 2012).
sarcoma (4 papers, 2008 to 2024). A usually aggressive malignant neoplasm of the soft tissue or bone. "Due to the fact that more than 60% of sarcomas have PML body expression, PML may be associated with pathogenesis and/or tumor behavior of sarcomas." (PMID 19025608, 2008). "PML body expression rates of all sarcoma cells were 1.5 ± 1.8% (range: 0–7.0) in MFH and 1.3 ± 1.4% (0–5.2) in liposarcoma samples." (PMID 19025608, 2008). "PML body expression rates of all sarcoma cells were 1.5 ± 1.8% (range: 0–7.0) in MFHs and 1.3 ± 1.4% (0–5.2) in liposarcomas." (PMID 19025608, 2008). "Our results are based on a small number of samples, so additional research of PML functions for sarcomas is warranted." (PMID 19025608, 2008). "Therefore, we hypothesize that increased expression of PML in sarcomas may be secondary to the secretion of cytokines and relate to cellular growth and proliferation." (PMID 19025608, 2008). "Therefore, sarcomas also may influence PML bodies and PML may play an important role for tumorigenesis in sarcomas." (PMID 19025608, 2008). "In summary, PML bodies may be a useful objective marker in the assessment of sarcoma prognosis." (PMID 19025608, 2008). "The success stories with targeted therapies directed against PML::RARA and BCR::ABL in acute promyelocytic and chronic lymphocytic leukemia, respectively, but also the more recent clinical experience with inhibitors of kinase fusion proteins found in sarcoma, underscore this notion." (PMID 38611033, 2024). "Although the expression of PML is not directly associated with APB, the association of the ALT with the PML may influence the prognosis of sarcomas." (PMID 19025608, 2008). "However, little is known concerning expression of PML bodies in sarcomas, including whether or not expression can be used as a prognostic indicator of sarcomas." (PMID 19025608, 2008).
adenovirus infection (3 papers, 2010 to 2025). "In adenovirus infection, Ad protein E4-orf3 binds and redistributes PML NBs to filamentous structures." (PMID 40650119, 2025). "During prior investigations of our group, we were already able to show the significant impact of ATO treatment on human adenovirus infection, which is proposed to be based on a reorganization of PML-NBs and deregulation of the host cellular SUMO pool." (PMID 38567974, 2024). "Interestingly, this region overlaps the aa sequence of PML II that previously has been shown to be targeted by the Adenovirus 5-encoded protein E4 Orf3, a factor that contributes to distortion of PML NBs during the course of adenovirus infection." (PMID 21092142, 2010). "Interestingly, the region of PMLII that we found to be responsible for inducing nuclear periphery targeting overlaps the amino acid sequences previously shown to interact directly with the adenovirus protein E4 Orf3, which is known to be involved in PML NB disruption during adenovirus infection." (PMID 21092142, 2010).
cervical carcinoma (3 papers, 2014 to 2021). A carcinoma arising from either the exocervical squamous epithelium or the endocervical glandular epithelium. "To investigate the biological role of PML-II in IFNα-induced cell death, we employed PML-II specific siRNA in HeLa cells, which are a cervical cancer cell line that has been shown to express PML-II and to be susceptible to IFNα-induced apoptosis; PML-II is a major PML isoform in these cells." (PMID 34215258, 2021). "This pattern is highly reminiscent of the product of the immediate early gene X1 (IEX-1/IER3), which was previously reported to sequester MCL-1 in response to DNA damage, at least partially co-localizing with PML bodies in HeLa cervical carcinoma cells." (PMID 30123424, 2018).
COVID-19 (3 papers, 2021 to 2024). A disease caused by infection with severe acute respiratory syndrome coronavirus 2. "Recent investigations report an elevated expression of genes encoding IRF1, IRF5, IRF7, JAK2, and PML in severe COVID-19 patients." (PMID 38022551, 2023). "However, PML and RSAD2 expression levels were significantly upregulated in COVID-19 patients bearing high and medium viral load." (PMID 34446714, 2021).
dyslipidemia (3 papers, 2018 to 2023). "Collectively, these data indicate that APL cells elevate lipid levels in APL mice and that PML-RARα acts as the core factor causing the dyslipidemia associated with APL." (PMID 32929351, 2020). "In this study, we verified the hypothesis that the metabolic stress sensor TRIB3 collaborates with the oncoprotein PML-RARα to inhibit PPARγ activity and subsequently cause dyslipidemia in newly diagnosed APL patients." (PMID 32929351, 2020). "Although arsenic/ATRA therapy degraded PML-RARα and restored PPARγ expression, it exacerbated dyslipidemia in APL patients." (PMID 32929351, 2020). "The TRIB3 expression that was increased by ATRA/As2O3 treatment further impeded PPARγ activity by forming the heterotrimer of TRIB3, PML-RARα and PPARγ, contributing to dyslipidemia in APL patients undergoing anti-APL therapy." (PMID 32929351, 2020). "In summary, our study not only reveals a critical role of the PML-RARα/PPARγ/TRIB3 axis in dyslipidemia for patients with APL but also confers a rationale for the combination of ATRA/arsenic with the PPAR activator for the treatment of patients with APL." (PMID 32929351, 2020). "Therefore, we herein hypothesize that the increased TRIB3 expression functions together with PML-RARα to participate in the regulation of dyslipidemia in patients with APL." (PMID 32929351, 2020). "Given that PML-RARα inhibited PPARγ activity in APL cells, we next examined whether ATRA/As2O3 rescued PPARγ activity and improved dyslipidemia in APL patients by decreasing PML-RARα expression." (PMID 32929351, 2020). "However, although ATRA/arsenic treatment degraded PML-RARα and restored PPARγ expression, it did not improve but rather exacerbated dyslipidemia in these APL patients." (PMID 32929351, 2020). "The observation that anti-APL therapy reduced PML-RARα and enhanced PPARγ but could not normalize dyslipidemia in APL patients indicates that other important regulator(s) may participate in the regulation of lipid metabolism disorder in APL patients during induction therapy." (PMID 32929351, 2020).
heart failure (3 papers, 2021 to 2023). Inability of the heart to pump blood at an adequate rate to meet tissue metabolic requirements. "Our previous study uncovered that promyelocytic leukemia protein (PML)-associated SUMO processes is a new regulator of cardiac hypertrophy and heart failure." (PMID 36778116, 2023).
Hutchinson-Gilford progeria syndrome (3 papers, 2018 to 2022). "Senescence-associated PML-lamina threads occur in Hutchinson-Gilford progeria syndrome (HGPS), a premature aging syndrome resulting from disruption of nuclear lamina integrity." (PMID 35178392, 2022). "Progerin, a truncated form of lamin A, has been shown to colocalize with aberrant toroid-like and thread-like PML-NBs in fibroblasts obtained from Hutchinson-Gilford progeria syndrome patients, suggesting that the topology of PML-NBs may be linked with some pathological consequences." (PMID 35594310, 2022).
Immunodeficiency (3 papers, 2018 to 2022). Failure of the immune system to protect the body adequately from infection, due to the absence or insufficiency of some component process or substance. "For example, in immunodeficiency, centromeric region instability, facial anomalies syndrome (ICF), and several other diseases, giant toroidal PML bodies are formed, containing, in addition to the main PML body proteins, uncoded heterochromatin." (PMID 34072343, 2021).
liposarcoma (3 papers, 2008 to 2025). A usually painless malignant tumor that arises from adipose tissue. "We present the results of an analysis of the clinical significance of PML body expression in primary tumor samples from malignant fibrous histiocytoma and liposarcoma patients." (PMID 19025608, 2008). "In our present study, PML body immunostaining was identified in 23 of 36 MFHs (63.9%) and in 12 of 19 (63.2%) liposarcomas." (PMID 19025608, 2008). "Immunofluorescence of PML body immunostaining on paraffin sections identified 23 of 36 tumors (63.9%) in MFHs and 12 of 19 (63.2%) in liposarcomas." (PMID 19025608, 2008). "A total of 27 liposarcoma tissue samples were collected from 27 different patients and evaluated for telomerase activity using the TRAP assay and for the ALT phenotype using immunofluorescence/FISH to detect ALT-associated PML bodies." (PMID 18414473, 2008). "We studied MFH and liposarcoma samples from 55 patients for PML bodies." (PMID 19025608, 2008). "This study was undertaken to analyze the clinical significance of PML body expression in primary tumor samples from malignant fibrous histiocytoma (MFH) and liposarcoma patients." (PMID 19025608, 2008). "Our study suggests that the presence of PML bodies may indicate a poor prognosis for MFH and liposarcoma patients." (PMID 19025608, 2008). "In our study, PML body expression (p = 0.0053) and a high rate of PML body expression (p = 0.0012) were significant prognostic risk factors for death in MFH patients, and all liposarcoma patients without expression of PML were alive at the end of the study." (PMID 19025608, 2008). "All liposarcoma patients who had no PML body expression were disease free." (PMID 19025608, 2008). "All liposarcoma patients without expression of PML were disease free at the end of the study." (PMID 19025608, 2008).
Listeria infection (3 papers, 2013 to 2021). "A subsequent study revealed that SUMOylation status of PML largely serves as a sensor of Listeria infection." (PMID 34513832, 2021). "Using transcriptomic and proteomic microarrays, we also characterized a network of immunity genes and cytokines, which are regulated by PML in response to Listeria infection but independently from the listeriolysin O toxin." (PMID 28074026, 2017). "In the case of Listeria infection, we demonstrated that host plasma membrane perforation by LLO triggers PML oxidation, multimerization, and association with the nuclear matrix, in striking similarity to the results of arsenic trioxide exposure." (PMID 28074026, 2017). "By studying MEFs’ responses to Listeria infection, we characterized a network of genes and cytokines that are involved in innate immunity and regulated by PML." (PMID 28074026, 2017). "Together, these data highlight that PML specifically restricts Listeria infection both in vitro and in vivo." (PMID 28074026, 2017). "It has been reported that PML knockout mice react to staphylococcus and listeria infection by hyperproliferative response resulting in the development of splenomegaly." (PMID 23555679, 2013). "PML knockout mice have been found to be more sensitive to infection by Listeria monocytogenes, a Gram-positive bacterium that is responsible for the foodborne disease listeriosis." (PMID 34513832, 2021). "In this study, we demonstrate that PML restricts Listeria infection both in vitro and in vivo." (PMID 28074026, 2017). "This confirms our results showing that PML-dependent genes modulated in response to Listeria infection are independent of LLO." (PMID 28074026, 2017). "Taken together, these data establish that PML de-SUMOylation impairs Listeria infection in the host cell, thereby supporting our hypothesis that LLO-induced PML SUMO deconjugation is a contributor to bacterial replication dampening." (PMID 28074026, 2017). "This suggests that PML does not regulate NF-kB genes in the context of Listeria infection." (PMID 28074026, 2017).
lung adenocarcinoma (3 papers, 2013 to 2023). A carcinoma that arises from the lung and is characterized by the presence of malignant glandular epithelial cells. "Non-small cell lung carcinoma tumorigenesis driven by the oncogene K-RasG12D, for example, benefits from PML loss, which leads to an increased number of lung adenocarcinomas." (PMID 23847764, 2013).
multiple sclerosis (3 papers, 2011 to 2017). A progressive autoimmune disorder affecting the central nervous system resulting in demyelination. "No study examined samples from the HIV-negative PML group, or patients with multiple sclerosis." (PMID 21436884, 2011).
non-small cell lung carcinoma (3 papers, 2012 to 2013). A group of at least three distinct histological types of lung cancer, including non-small cell squamous cell carcinoma, adenocarcinoma, and large cell carcinoma. "In human cancers, aberrant activation of CK2 is found in a subset of non-small cell lung cancer (NSCLC) cell lines and patient specimens, which correlates with decreased PML protein levels." (PMID 22935031, 2012). "SUMOylated PML also primes casein kinase 2 (CK2)-mediated phosphorylation of PML, which also contributes to ubiquitination-mediated PML degradation as shown in APL cells, non-small cell lung carcinoma cells and human primary tumor specimens." (PMID 23316480, 2012).
poliovirus infection (3 papers, 2013 to 2019). An disease or disorder caused by infection with Enterovirus C. "Note that poliovirus infection also very rapidly induces PML phosphorylation by the ERK1/2 pathway, followed by the transfer of PML from the nucleoplasm to the nuclear matrix." (PMID 23734343, 2013).
prostate adenocarcinoma (3 papers, 2012 to 2021). "This peptide inhibitor, or other inhibitors of E6AP, can be used to test the possibility of relieving PML from proteasomal destruction in cancers where E6AP is elevated such as prostate adenocarcinoma and B-lymphoma." (PMID 23730625, 2013).
soft tissue sarcoma (3 papers, 2008 to 2024). A malignant neoplasm arising from muscle tissue, adipose tissue, blood vessels, fibrous tissue, or other supportive tissues excluding the bones. "PML detection by immunofluorescence staining in paraffin embedded tissues, in soft tissue sarcoma samples, was shown to be a prognostic marker of poor overall survival." (PMID 29273061, 2017). "However, in our present study, the PML body expression for patients correlates more strongly with a worse prognosis than these clinical factors, so that the presence of PML bodies indicated the likelihood of poor outcomes in patients with soft tissue sarcomas." (PMID 19025608, 2008).
thalassemia (3 papers, 2017 to 2022). An inherited blood disorder characterized by a decreased synthesis of one of the polypeptide chains that form hemoglobin. "Other components of PML-NBs, such as alpha-thalassemia/mental retardation syndrome X-linked protein (ATRX), PML protein, and SP100 nuclear antigen modify chromatin and act as repressors of MIE gene expression." (PMID 33113934, 2020).
bladder cancer (2 papers, 2011 to 2015). "Five years after the discovery of the Pml gene, the tumor suppressive activity of PML was demonstrated in several cancer types including breast, lung, colorectal, prostate and bladder cancer." (PMID 26539288, 2015).
brain cancer (2 papers, 2021 to 2023). A primary or metastatic malignant neoplasm affecting the brain. "We found that the two H3.3 point mutations (G34R/K27M) which are common in pediatric brain cancers disrupted the formation of PML-NBs." (PMID 38066546, 2023).
breast adenocarcinoma (2 papers, 2013 to 2018). "In addition, PML low-expression correlates with bad prognosis and high-grade tumors for breast adenocarcinomas and prostate carcinomas." (PMID 23847764, 2013).
chronic hepatitis (2 papers, 2016 to 2023). An active inflammatory process affecting the liver for more than six months. "The involvement of PML protein in the early stage of hepatocarcinogenesis and HBV infection and the possible association of HBV infection with PML overexpression or changes in PML NB morphology was revealed by the analysis of human HCC, liver cirrhosis, and chronic hepatitis samples." (PMID 37127643, 2023). "Conversely, in the subsequent phases of chronic hepatitis, inactive carrier and HCC development, a gradual-to-total disappearance or downregulation of HBsAg was accompanied by re-appearance of nuclear PML." (PMID 27058621, 2016).
clear cell renal carcinoma (2 papers, 2024). A malignant epithelial neoplasm of the kidney characterized by the presence of lipid-containing clear cells within a vascular network. "When PML is dephosphorylated at Ser518 by the phosphatase SCP1, Pin1 and KLHL20 are unable to mediate the ubiquitination and degradation of PML, thereby inhibiting the progression and growth of both in vitro and in vivo clear-cell renal carcinoma models." (PMID 38727267, 2024).
colon adenocarcinoma (2 papers, 2012 to 2014). "SENP3 has been identified to accumulate in a variety of types of primary human cancer, including colon adenocarcinoma, by modulating the SUMOylation status of the tumor suppressor, promyelocytic leukemia protein (PML)." (PMID 24926368, 2014).
Frontotemporal lobar degeneration (2 papers, 2022 to 2023). "TRIM19/PML removes a variety of protein aggregates in the nucleus associated with NDs such as HD, ALS, and frontotemporal lobar degeneration with ubiquitinated inclusions (FTLD-U)." (PMID 35946309, 2022). "In addition, compared to control subjects the expression levels of PML, Ubc9, and SUMO1 were also not significantly different in the frontal cortex tissue from a cohort of patients affected by Frontotemporal lobar degeneration (FTLD), regardless of the C9orf72 repeat expansion." (PMID 37454169, 2023).
herpes zoster (2 papers, 2011). A common dermal and neurologic disorder caused by reactivation of the varicella-zoster virus that has remained dormant within dorsal root ganglia, often for decades, after the patient's initial exposure to the virus in the form of varicella (chickenpox). "From a clinical perspective, it is notable that patients treated with arsenicals have an extremely high rate of clinically symptomatic herpes zoster, due to VZV reactivation and arsenicals are potent triggers of PML degradation." (PMID 21304940, 2011). "We suggest that PML NB-mediated control of VZV replication must be counteracted by ORF61 in order to produce the characteristic cutaneous lesions of varicella and herpes zoster and that ORF61 SUMO-binding capacity is necessary for this essential phase of the VZV life cycle in the human host." (PMID 21901090, 2011).